IL10 (interleukin 10)
Diseases named in the same sentence as IL10 in open-access papers (continued):
Sharing a sentence is not in itself a finding about the gene and the disease.
tumor (continued). "Tumor-associated Tregs express the IL-23 receptor, which activates Stat3, resulting in the upregulation of the Treg-specific transcription factor Foxp3 and the immunosuppressive cytokine IL-10." (PMID 24586528, 2014). "Our results suggest that mutations that disrupt the interactions of IL-10 with its receptors (IL-10RA and IL-10RB) and α2-macroglobulin (A2M) may enhance inflammation and modulate anti-tumor immunity." (PMID 25056661, 2014). "Lastly, the induction of CHS at the tumor site could cause the infiltration of hapten-specific T-regs, which could potentially release IL-10 to suppress effector T-cells or elicit CD8+ T-cell exhaustion by expression of CTLA-4." (PMID 24949488, 2014). "IL-10 deficiency leads to an increase in the number of Tregs and MDSCs in tumor tissue." (PMID 25056661, 2014). "Based on these results, we arrived to the conclusion that a combinatorial treatment associating Treg counteraction, through IL-10 blockade, with stimulation of the anti-tumor immune response, through vaccination, could have addictive/synergic efficacy." (PMID 23663506, 2013). "These analyses showed that in both tumor microenvironments, IL-10 treatment caused a significant increase of CD4+granzyme+ T cells with a concomitant decrease of CD4+CD25+FoxP3+ Treg, reminiscent of what observed after vaccination with gp10025-33 peptide-pulsed DC." (PMID 23663506, 2013). "Altogether, these data point to different tumor-associated factors (i.e., IL-10, IL-6, PGE2) exerting their suppressive effects at various stages of myeloid DC development through converging and communicating signaling elements encompassing the JAK2/STAT3 and p38-MAPK pathways." (PMID 24324467, 2013). "IL-10 is critically involved in the establishment of tumor-associated immune suppression, and we have clearly demonstrated IL-10 production by around 40% of tumor-infiltrating Treg in murine transplanted tumors." (PMID 23986759, 2013). "One possible explanation for the discrepancy is that carcinogenic mechanism underlying the etiology may differ by different tumor sites and that the IL-10 genetic variants may play a different role in different cancers." (PMID 23460834, 2013). "Indeed, the IL-10-conditioned CD14+ DDC with a DC-SIGN+BDCA3+CD163+ phenotype are highly reminiscent of both tumor-associated macrophages and DC, adopting similar M2-like immunosuppressive traits." (PMID 23875023, 2013). "Additionally, inhibition of T cell effector activity by tumor-associated regulatory DC has also been associated with increased IL-10 secretion by these cells." (PMID 23874338, 2013). "However, after adjusting for serum levels of IL17, IL10, as well as the other general clinicopathological factors, the risk remained statistically significant for tumor size only (adjusted HR = 2.00, 95% CI 1.09–3.68)." (PMID 23227158, 2012). "Additionally, it has been reported that IL-10 decreases the ability of epidermal antigen presenting cells (APCs) to present tumor-associated antigens, therefore interfering the induction of antitumor immune responses." (PMID 23316105, 2012). "Tumor-associated plasmacytoid DC also induced IL-10+ TReg generation." (PMID 22481922, 2012). "The inhibition of tumour-generated CD4+ TReg cells through abolition of cell-to-cell contact was associated with a reduction in the production of IL-10 (69.8±33.6 pg/ml vs 6.3±0.01 pg/ml, n = 3, p = 0.079) and IFNγ (12154±4174 pg/ml vs 0.04±0.01 pg/ml, n = 3, p<0.001)." (PMID 22666318, 2012). "IL-10 is associated with tumor malignancy via immune escape." (PMID 22848356, 2012). "This indicated that IRE treatment, like tumor resection, could release the immunosuppression caused by high IL-10." (PMID 23139816, 2012). "Conversely, in IL-10-deficient tumor-bearing mice the defect in DC function was reversed." (PMID 22592077, 2012). "This may be associated with the observation that the number of tumor-infiltrating lymphocytes was decreased in the tumors with higher levels of IL-10." (PMID 22848356, 2012).
tumor (continued). "Furthermore, it has been reported that IL-10 decreases the ability of epidermal APCs to present tumor-associated antigens for the induction of antitumor immune responses in a spindle cell tumor system." (PMID 22778768, 2012). "In addition, many tumors contain tumor-associated macrophages (TAMs) that are also suppressors of tumor immunity through production of IL-10, stimulation of Treg, and synthesis of the coinhibitory factor CTLA-4." (PMID 23056925, 2012). "Interestingly, high levels of serum IL-10 were associated with anti-tumor response in a clinical trial involving metastatic melanoma patients treated with immunochemotherapy (i.e., bevacizumab and fotemustine)." (PMID 21992116, 2011). "Therefore the role IL-10 plays on TC-1 tumor growth is probably associated only to the regulation of immune responses and its source, as demonstrated in this work, is the myeloid tumor infiltrate." (PMID 20525400, 2010). "In parallel to a reduction in tumor growth, we observed in IL-10 deficient mice or mice treated with anti-IL-10/anti-IL-10R neutralizing antibodies that there was an increase tumor infiltration by CD4 and CD8 lymphocytes, which were rare in tumors from control wild type mice." (PMID 20525400, 2010). "There was, for example, a significant increase in the CD11b+ myeloid population in IL-10 deficient mice and mice treated with anti-IL-10/IL-10R neutralizing antibodies when compared to controls, indicating a difference in the tumor microenvironment due to IL-10 depletion." (PMID 20525400, 2010). "We next asked whether the decrease in tumor growth in IL-10 deficient mice or mice treated with neutralizing anti-IL-10/IL-10R had any effect on lymphocyte populations." (PMID 20525400, 2010). "For instance, in vivo, treatment of tumor-bearing animals with interleukin-12 (IL-12) shifts tumor-associated macrophages from a dominant M2 profile (elevated expression of TGFβ, IL-10, and MCP1) to a proimmunogenic/inflammatory M1 profile (elevated expression of IL-6 and TNFα)." (PMID 20508742, 2010). "Tumour-associated macrophages are derived from circulating monocytes and are activated macrophages of the polarised type II (type II or M2 macrophages) induced by IL-4, IL-13 (M2a) or IL-10 (M2c) and glucocorticoid hormones." (PMID 16832418, 2006). "Additionally, analyses of 3 CRC spatial transcriptomics datasets revealed a high degree of spatial colocalization among SENP7, IL-10, and CD20, suggesting a potential spatial association between SENP7-expressing B cells and IL-10 production within the tumor microenvironment." (PMID 41362746, 2026). "In contrast, high levels of immunosuppressive cytokines like IL-10 (and certain pro-tumor chemokines such as IL-8, which can recruit suppressive myeloid cells) are associated with poorer outcomes, potentially by promoting T-cell exhaustion and tumor immune evasion." (PMID 41020868, 2025). "Moreover, depletion of bulk Treg cells may consequently induce conventional CD4+ T cells to express the immunosuppressive cytokine IL-10, causing a paradoxical immunosuppressive barrier to anti-tumor immunity." (PMID 40468052, 2025). "Similarly, the expression of Il10, which encodes another anti-inflammatory pro-tumor marker, was slightly upregulated (up to four-fold compared to HS) in the RLS40Low and RLS40Med subgroups and at the level of healthy control (HS) in the RLS40High and RLS40/D subgroups." (PMID 40867260, 2025). "Tumor-associated macrophages (TAMs), microglia, and myeloid-derived suppressor cells (MDSCs) constitute the major immunosuppressive axis, promoting tumor progression through cytokine secretion (IL-10, TGF-β), metabolic reprogramming, and inhibition of cytotoxic immunity." (PMID 40787444, 2025).
tumor (continued). "Finally, myeloid-derived suppressor cells and tumor-associated macrophages contribute to immunosuppressive tumor microenvironments by releasing IL-10, TGF-β, arginase, and VEGF, affecting both species and providing a rationale for cross-species evaluation of immune therapies." (PMID 40725420, 2025). "Thus, this HCMV-modulated cytokine demonstrates context-specific activity with tolerogenic properties in the context of autoimmunity, whilst being directly implicated in anti-tumour responses; whether vIL-10 mimics all diverse actions of IL-10 is unclear." (PMID 41194666, 2025). "Therefore, an elevated IL-10/IL-6 serum ratio may help exclude patients with underlying systemic infection or inflammation, thereby improving specificity for tumor-associated cytokine imbalances." (PMID 40881684, 2025). "Interleukin-10 (IL-10), often described as a cytokine with inhibitory effects, plays a pivotal role in modulating inflammation and infectious disease outcomes, and it is also involved in the suppression of pro-tumor inflammatory responses, as well as the regulation of tumor-associated angiogenesis." (PMID 40869161, 2025). "This properdin deficiency results in low levels of IL-1b mRNA and higher levels of arginase-1, monocyte chemotactic protein-1 (MCP-1), and IL-10 mRNAs, suggesting that a properdin-deficient tumor microenvironment may induce a profile of M2 macrophages with pro-tumoral activity." (PMID 40370471, 2025). "Moreover, its association with markers of apoptosis indicates that IL-10 may facilitate tumor survival by inhibiting the programmed death of cancer cells, which contributes to increased tumor aggressiveness." (PMID 39456897, 2024). "KCs respond to antigenic, damage-associated, or microbe-derived signals by secreting IL-10 and other immunosuppressive cytokines, and they express the immune checkpoint ligand PD-L1, which significantly hampers the immune system’s capacity to identify and eliminate tumor cells." (PMID 39691767, 2024). "In addition, tumor cells, tumor-associated macrophages, and Treg cells often produce IL-10 or shed gangliosides, which may also preclude optimal DC maturation and function." (PMID 38927447, 2024). "Within a tumour microenvironment, tumour-associated macrophages (TAMs) make up a significant part of M2 macrophages and regulate pro-tumour mechanisms by secreting anti-inflammatory cytokines, such as interleukin-10 (IL-10), resulting in increased tumorigenesis." (PMID 38169974, 2024). "Indeed, c-FLIP in tumour-reprogrammed monocytes does not only act as anti-apoptotic protein but also drives a marked regulation of genes encoding for immunosuppression-associated factors, like PD-L1, PD-L2, and IL-10." (PMID 36161514, 2023). "However, IL10 increase in HES1 (−) tumors may implicate the complex tumor microenvironment remodeled by KRAS mutation and/or HES1-loss." (PMID 37749297, 2023). "Tumor-associated macrophages (TAMs) derive from circulating monocytic precursors, infiltrating macrophages in tumor tissue are driven by tumor-derived cytokines (e.g. IL-10, TGF-β) and T cell-derived cytokines (e.g. IL-4, IL-13) and acquire a polarized M2 phenotype." (PMID 37691932, 2023). "The secretion of immunosuppressive cytokines (TGF-β, IL-10) and the presence of immune-suppressive cells – like tumor-associated macrophages/microglia (TAMs) and myeloid-derived suppressor cells (MDSCs) - limit the effectiveness of immune system to eradicate tumor cells." (PMID 35603195, 2022). "Tumor cells evade immune cells through various mechanisms, including inhibition or loss of tumor antigens, the release of immunosuppressive extracellular vesicles such as exosomes, the release of immunosuppressive molecules such as interleukin-10, and transforming growth factor (TGF)." (PMID 35832550, 2022).
tumor (continued). "Macrophages and particularly M2 tumor-associated macrophages (TAMs) with protumor effects are responsible for Treg differentiation and are able to create an immunosuppressive environment favoring tumor growth, notably through the secretion of cytokines (IL-10, TGFβ, TNFα)." (PMID 36428652, 2022). "Furthermore, IL-10-producing Breg cells have been shown to contribute to tumor progression by positively regulating the differentiation of tumor-associated macrophages (TAMs), skewed toward a M2 macrophage phenotype, that ultimately inhibit effector T and NK cells." (PMID 34164398, 2021). "In particular, TGF- β and IL-10 mediate an anti-inflammatory response by dampening the activity of tumor suppressor cells, such as cytotoxic T lymphocytes (CTLs) and NK cells, and enhancing the activity of tumor-promoting cells such as Tregs and tumor-associated neutrophils (TANs)." (PMID 33802281, 2021). "Significant decreases in the expression of cytokines are associated with tumor-associated macrophages (TAMs), including IL-4, IL-10 CCL-2, CCL-22, and CXCl-12, and suggest that the reduction in macrophages within the treated tumors could be indicative of a decrease in TAMs." (PMID 33956631, 2021). "IL-10-producing EBNA1-specific T cells that were enriched in children with eBL might be involved in preventing efficient immune control of this EBV-associated tumor." (PMID 34771539, 2021). "One possible explanation is that IgG4 produced in tumor microenvironment and stroma may be associated with chronic antigen challenge associated with Th2 cytokines including IL-4, IL-10, and IL-13, which causes inappropriate host immune tolerance against malignancies and tumor progression." (PMID 33920932, 2021). "In patients with HCC, anti-inflammatory compounds, including regulatory T (Treg) cells, tumor-associated macrophages (TAMs), myeloid-derived suppressor cells, and liver sinusoidal endothelial cells, express cytokines, such as interleukin- (IL-) 6, IL-10, and transforming growth factor- (TGF-) β." (PMID 32595757, 2020). "However, for the experiment that compared inflammation, invasion, and neoplasia in azoxymethane (AOM)-treated interleukin-10-deficient mice mono-associated with NC101 or NC101Δpks the experimental timing of the replication attempt was longer than that of the original study." (PMID 30295289, 2018). "In addition, the overexpression of IL-10 in the tumor was associated with an increase in tumor cell proliferation, and immune evasion, which corroborates our findings indicating a possible correlation between overexpression of IL-10 and tumor development." (PMID 30112116, 2018). "Importantly, increases in TNFα, IL-12p70 and IL-2 are not merely consequent of enhanced immune cell presence, as a number of other cytokines were unaltered by ibuprofen treatment including those associated with tumor associated macrophages, monocytes and M2 polarized macrophages [IL-4, IL-6, IL-10]." (PMID 30285905, 2018). "In addition, elderly tumor-associated CD11c+ cells may be further skewed toward suppressive function due to increased IL-10 and TNF-α." (PMID 30560130, 2018). "Besides, tumor-associated macrophages (TAM) protect the tumor from immune responses by various mechanisms including the release of anti-inflammatory interleukin-10 and the expression of surface receptors like programmed death-ligand 1 which inhibit the functions of activated T cells." (PMID 30445702, 2018). "On the other hand, IL-10, IL-17 and TNFα, though some studies indicate that they activate cell growth, they have been associated with blocking apoptosis, inhibiting antigen presenting cells, inhibiting cytokine production, favour tumor growth and promote inflammation." (PMID 29246138, 2017).
tumor (continued). "Blood and tumor TEM display a mixed M1-like (tumor-associated macrophages releasing inflammatory molecules) and M2-like (immunosuppressive macrophages polarized by anti-inflammatory molecules) phenotype, with secretion of both the pro- and anti-inflammatory cytokines IL-12 and IL-10, respectively." (PMID 25768678, 2015). "Likewise, elevated IL-10 levels are associated with poor prognosis in diffuse B cell lymphoma and expression by tumor cells, and tumor-associated macrophages promote Burkitt's lymphoma through the increased production of a TNF-α family member, BAFF, a tumor growth/survival molecule." (PMID 24901008, 2014). "However, testing a panel of tumor-associated culprits pointed to IL-10 as the most likely candidate, since it was the only tested cytokine that could affect the balance of migrating CD1a+ and CD14+ DDC." (PMID 23875023, 2013). "In addition, the analysis of a uniformly treated group of patients showed that the presence of EBV in tumor cells was associated with a favorable outcome, especially in the advanced risk group, while IL10.01 family and IL10.G12 allele were associated to an unfavorable outcome." (PMID 23029361, 2012). "Constitutional IL-10 promoter polymorphisms have been associated with the susceptibility to certain malignancies, suggesting that this cytokine may play a critical role in some aspect of tumor immunosurveillance." (PMID 24213115, 2011). "It is possible that IL-10 causes a skewing in adaptive response toward humoral response, which may contribute to the inhibition of T cell function or simply which is ineffective against tumor cells." (PMID 20525400, 2010). "Tumor volume and morphological changes in various organs were observed, and the serum concentrations of IL-6, IL-10, and TNF-α were assessed." (PMID 41901226, 2026). "In a murine 4T1 breast cancer model, tumor-induced Bregs (tBregs) were found to secrete IL-10 and TGF-β, which drives the conversion of conventional CD4+ T cells into immunosuppressive FoxP3+ Tregs." (PMID 41614936, 2026). "IL‐10 reduces macrophage IL‐12 secretion, reprogramming them from antitumour M1 to pro‐tumour M2 states." (PMID 41491612, 2026). "Excessive IL‐10 signalling impairs IL‐12 secretion and abolishes cross‐presentation capacity in tumour‐infiltrating CD103+cDC1 subsets, ultimately leading to T cell dysfunction." (PMID 41491612, 2026). "In parallel, HHLA2 reshapes the tumor microenvironment through interleukin-10-dependent macrophage M2 polarization, contributing to an immunosuppressive niche." (PMID 42266686, 2026). "Elevated PD-1 expression in protumorigenic regulatory B cells suppresses tumor-specific T-cell immunity by secreting immunosuppressive cytokine IL-10." (PMID 41486149, 2026). "scRNA-seq revealed cell-type-specific expression patterns, where IL1B was significantly upregulated in both tumor epithelial and myeloid cells, and IL10 was specifically elevated in tumor epithelial cells." (PMID 41983192, 2026). "This immunomodulatory effect is closely related to CDKN2A expression levels—high expression allows tumor cells to secrete IL-10, which can induce Treg differentiation, further weakening the anti-tumor immune response." (PMID 41601652, 2026). "In mice, BPA markedly inhibited the growth of syngeneic CRC tumors, accompanied by decreased serum levels of the immunosuppressive cytokine IL-10 and reduced expression of the proliferative marker Ki67 in tumor tissues." (PMID 41597201, 2026). "In lung cancer, TAMs secrete IL‐10, which supports tumor cell proliferation through the JAK1/STAT1/NF‐κB/Notch1 pathway." (PMID 41426206, 2026). "Regulatory B-cell (Breg)-derived IL-10 is a crucial immunosuppressive factor that suppresses CD8+ T-cell function in the tumour microenvironment (TME), facilitating immune evasion." (PMID 41362746, 2026). "For instance, in human HCC, a PD-1hi Breg subset was shown to curtail tumor-specific T-cell immunity via IL-10 production, thereby promoting tumor progression." (PMID 41614936, 2026).